MICA (MHC class I polypeptide-related sequence A)
Diseases named in the same sentence as MICA in open-access papers (continued):
Sharing a sentence is not in itself a finding about the gene and the disease.
tumor (continued). "These novel findings demonstrate that the interaction of CHK1 and IRF1 plays a key role in regulating the tumor immune microenvironment through MICA in HCC." (PMID 36765808, 2023). "Major histocompatibility complex class I chain-related protein A (MICA) is the human ligand for the NKG2D receptor on NK cells, and binding of MICA triggers NK cells and enhances antigen-specific tumor immunity." (PMID 37234162, 2023). "Although MICA can be shed at the surface of cancer cells during tumour development and progression, miRNA regulation is another important mechanism that disrupts MICA expression." (PMID 37784183, 2023). "Tumor cells commonly express stress-inducing molecules, such as NK ligands, including MHC class I polypeptide-related sequence A (MICA), MICB, and UL16-binding proteins (ULBPs), which selectively activate NK cells through the NKG2D receptor." (PMID 37876793, 2023). "Unfortunately, tumor cells have various mechanisms to evade immune surveillance, and one of them is cleavage of MICA/MICB from the cell membrane using surface proteases." (PMID 38033491, 2023). "NK cells recognize tumor cells through their NKG2D receptor binding to its ligand, MHC class I-polypeptide related sequence A or B (MICA/MICB) which are expressed on the surface of tumor cells." (PMID 36830840, 2023). "A third recently described mechanism by which tumour cells can reduce MICA and MICB expression involves neddylation." (PMID 37626965, 2023). "STAT3 from tumour cells can reduce anti-tumour immunity by suppressing MICA and generating pro-inflammatory chemokines." (PMID 37784183, 2023). "These cellular miRNAs are often aberrantly expressed in human tumour tissues and can inhibit MICA expression, which promotes tumour proliferation, apoptosis, differentiation, invasion, and metastasis, and can also aid in the avoidance of immune cell attack." (PMID 37784183, 2023). "Recognition and killing of tumor cells: γδΤ cells are capable of recognizing stress-inducing molecules such as MICA, MICB, ULBP, and RAET1." (PMID 37597083, 2023). "Tumor cells escape NKG2D‐mediated tumor immune monitoring by promoting MICA/B shedding, which is often referred to as tumor immune escape." (PMID 37426678, 2023). "Silencing miR-183 and overexpression MICA contributed to the lysis of tumour cells by activated CD8+ T cells via the MICA-NKG2D pathway." (PMID 37784183, 2023). "Research shows that MICA is regulated by miRNAs in various cancers in which MICA and miRNAs often show aberrant expressions and contribute to the tumour proliferation, apoptosis, differentiation, invasion, and metastasis." (PMID 37784183, 2023). "Our findings shed light on the role of EV-associated MICA allelic variants and ULBP molecules in the modulation of NKG2D-mediated NK cell immunosurveillance in the tumor microenvironment." (PMID 37298418, 2023). "In any case, immune recognition through NKG2D can be restored by maintaining MICA in tumour cell surface." (PMID 37022605, 2023). "This study identified MICA shedding from the tumor cell surface as a mechanism to escape γδ T-cell recognition." (PMID 37139603, 2023). "According to our studies, this CHK1/IRF1/MICA axis activates anti-tumor immune cells to enhance tumor disruption through the interaction of miR-195." (PMID 36765808, 2023). "Among these proteins were: NKG2D, responsible for binding to MicA on the surface of the tumor cell and recognition of the target cell, FasL, responsible for the induction of cytotoxic signal via FasL-Fas interaction." (PMID 36653582, 2023). "Here we aimed to identify transcription factors susceptible to pharmacological stimulation resulting in the expression of the NKG2D-L MICA in AML cells to restore anti-tumor activity." (PMID 37143070, 2023). "Hypoxia inhibited the expression of heat shock protein 70 and MICA/B of tumor cells, which helped tumor cells escape recognition by NK cells." (PMID 38022646, 2023).
tumor (continued). "Tumor cells and primary MM cells treated with DRd for 24 h showed significantly increased expression of MICA, MICB, ULBP1, ULBP2, and Fas receptor compared to Rd or untreated tumor cells (all p < 0.0001)." (PMID 36385211, 2023). "Further examination of molecule expression patterns of infiltrated immune cells and tumor cells revealed that immunomodulatory antibodies targeting MICA/B and NKG2A had anti-tumor potential." (PMID 37016422, 2023). "The presence of miRNAs in extracellular vesicles suggest that MICA expression on tumor cells can be regulated by miRNA carried into EVs." (PMID 38146340, 2023). "Some studies indicated that shedding of MICA or other NKG2D ligands contributed to tumor immune escape by releasing soluble MICA (sMICA) molecules binding to NKG2D receptors and inducing its down-modulation and degradation." (PMID 36765808, 2023). "Due to its expression in various types of tumor, MICA presents an appealing target for immunotherapy." (PMID 37373430, 2023). "MICA expression was recently reported in many tumours and normal epithelial cells, but with predominantly intracellular localization and low cell surface expression." (PMID 37784183, 2023). "The extensive polymorphism of the MICA/B genes together with the diversity of stress inducers upregulating MICA/B and the 6 ULBPs, has challenged our understanding of their regulation, especially in the tumor microenvironment." (PMID 36980678, 2023). "MICA stimulation of NK cells leads to strong activation and tumour cell rejection with enhanced NKG2D-mediated cytotoxicity." (PMID 37784183, 2023). "A vaccine designed to induce antibodies that anchor MICA/B has been demonstrated to prevent tumor escape and enhance the function of tumor-reactive T cells and APCs." (PMID 37062844, 2023). "For example, studies report enhanced NK cell-mediated lysis via up-regulation of cell-surface MHC class I chain-related gene A/B (MICA/B) on tumor cells." (PMID 35327319, 2022). "Given the ability of the MICA/B antibody to promote anti-tumor immunity, we have recently applied 7C6 to pre-clinical models of AML." (PMID 36555547, 2022). "When cG7-MICA coupled to CD24 on tumor cells, inducing NK cell-mediated cytotoxicity, HCC cells were identified by NK cells via MICA." (PMID 36389699, 2022). "Dying tumor cells release cytokines type I IFNs, and the surface of the tumor cells is composed of ligands such as MICA/B and H60, which activate the immune system cells by binding to the receptors." (PMID 36362963, 2022). "During the apoptosis of tumor cells, MICA protein on the cell surface falls off and finally forms sMICA, which can hinder the killing activity of T cell subsets (CD8 +)." (PMID 35242806, 2022). "Chemotherapy-induced senescence upon MALAT1 knockdown similarly inhibited MICA/B secretion and enhanced NK sensitivity, demonstrating the potential clinical value of clearing senescent tumor cells." (PMID 35309907, 2022). "For example, interferon alpha (IFN-α) has been shown to enhance MICA expression on tumor cells through increased promoter activity." (PMID 35565467, 2022). "Several different HDACIs have also been shown to increase NK cell killing of tumor cells by upregulating the stress-inducing ligands, such as MICA, MICB, and ULBP1-3, in tumor cells from many different solid malignancies." (PMID 35140720, 2022). "The combination of NKG2D and MICA on tumor cells can enhance the tumor-killing activity and cytokine production of NK cells." (PMID 36119072, 2022). "The immunosuppressive TME of these 3D models contained of tumour cells, CAFs and immune cells accompanied by high expression of PD‐L1, PD‐L2 and reduced expression of MICA/B." (PMID 35731974, 2022). "Tumour cells shed MICA from their surface using ADAM protease, and therefore directly reduce the amount of activation ligand for NKG2D." (PMID 35806034, 2022).
tumor (continued). "Soluble form of MICA can be released by human tumor cells, causing the downregulation of NKG2D, which is considered to promote tumor immune evasion and also to compromise host resistance to infections." (PMID 36196481, 2022). "Hypoxia also impairs NK-mediated killing of tumor cells by downregulating and/or shedding the major histocompatibility complex (MHC) class I polypeptide-related sequence A (MICA) on the surface of cancer cells." (PMID 35795658, 2022). "Our findings showed that dramatic downregulation of exosomal PD-L1, E-cadherin, ULBP1, ULBP3, MICA, MICB, Siglec7 and significant upregulation of exosomal PD-1 and IFN-gamma were associated with tumor regression." (PMID 36741391, 2022). "First established using epithelial-derived tumors, MICA was shown to be actively released by tumor cells as a means of immunosuppression." (PMID 35565467, 2022). "The results showed that the expression of MICA was present in more than 75% of tumor cells of all studied CRC tumors." (PMID 35346234, 2022). "In particular, soluble MICA is overexpressed in the serum of MM patients, and its levels correlate with tumor progression." (PMID 35967396, 2022). "Gilteritinib selectively upregulated the expression of NKG2DLs (MICA/B and ULBPs), thereby increasing the tumour-killing capacity of CAR T cells." (PMID 35246156, 2022). "Inhibition of metalloproteinases reversed the shedding phenotype and promoted the accumulation of MICA on the tumor cell surface." (PMID 35565467, 2022). "In the HNSCC model we demonstrate that CHMP2A mediates tumor resistance to NK cells via secretion of extracellular vesicles (EVs) that express MICA/B and TRAIL." (PMID 35393416, 2022). "Tumor tissues often overexpress NKG2D ligands (MICA/B) that interact with the endogenous activating receptor NKG2D on NK cells." (PMID 36428748, 2022). "After NKG2D binds to its ligand, MHC class I chain-related molecules A/B (MICA/B), which expressed on the surface of target cells (namely tumor cells), NK cells can kill target cells and exert their immune surveillance function." (PMID 35692747, 2022). "Studies have shown that inhibition of the ADAM9 activity significantly blocked MICA shedding and affected the immune killing effect of NK cells on tumor cells." (PMID 36466812, 2022). "This phenomenon is explained mechanistically by the high expression of MALAT1 in senescent cells, which drives ADAM10 expression through the MALAT1/miR-92a/ADAM10 axis and the release of the ligand MICA/B from tumor cell membranes via hydrolysis." (PMID 35309907, 2022). "The combination enhanced NK cell-mediated tumor cell death through the induction of MICA, MICB and ULBP1-4." (PMID 35565467, 2022). "Targeting the NKG2D pathway has also been approached using different chimeric proteins where the ectodomain of MICA was fused to single chain Fv (scFv) against other molecules that promoted NK cell-mediated anti-tumor effects." (PMID 34394116, 2021). "Taken together, the data indicated that well-differentiated tumor cells expressed MICA/B, EGFR, and PDL1 and that the treatment of these tumors with their respective antibodies mediated ADCC by the NK cells." (PMID 33440654, 2021). "In this model MICAB1 Fc-engineered mAb was more potent than commercial anti-MICA/B mAb BAMO3 at controlling tumor cells with low level of MICA." (PMID 35967081, 2021). "Upregulation of MMP9 through p38 MAPK induces MICA cleavage and production of soluble MICA (sMICA), which decreases NK cell cytotoxicity favoring tumor immune escape." (PMID 33922633, 2021). "The underlying mechanisms involves the proteolytic shedding of MICA and other NKG2DL induced by tumor-secreted metalloproteases (MMP) or secretion in exosomes." (PMID 34394116, 2021). "CRISPR/Cas9-mediated transcriptional activation of MICA triggered the NK cell anti-tumor responses (ADCC can be mediated by genetic modifications)." (PMID 34572387, 2021).
tumor (continued). "In this study, we established that the levels of MICA/B expressions were higher on the surfaces of well-differentiated tumor cells than on stem-like/poorly differentiated tumor cells." (PMID 33440654, 2021). "Here, we evaluated NK cell-mediated cytotoxicity against CSCs/poorly differentiated and well-differentiated tumor cells treated with monoclonal antibodies specific for MICA/B." (PMID 33440654, 2021). "Hypoxia can up-regulate checkpoint molecules such as PD-L1 and down-regulate the NKG2D ligand MICA on tumor cells." (PMID 34572387, 2021). "Chemotherapeutic agents have also been shown to sensitize tumor cells to NK cell cytolysis through the induction of ligands on the tumor surface such as MICA/B, ULPBs and B7-H6 that bind activating NK receptors." (PMID 34497771, 2021). "MHC class I polypeptide-related sequence A (MICA) is a natural killer group 2D ligand (NKG2DL) expressed by tumor cells." (PMID 34540687, 2021). "Previous study showed a strong correlation between anticancer activity of Vγ9Vδ2 T cells and MICA/B expression on tumor cells in vitro." (PMID 34381711, 2021). "We have previously shown that the cytotoxicity of CIK cells was enhanced by stabilization of MICA/B on tumor cells through selective small-molecule inhibitors or a specific anti-MICA monoclonal antibody." (PMID 34691037, 2021). "In vivo mice models will also be included in the study of MICA-G129R for its circulation, tumor-targeting, NK cell-infiltration, efficacy and safety in inducing cytotoxicity and combination with other therapeutics." (PMID 34077462, 2021). "It becomes immobilized and enriched in breath tumor just like the MICA expressed on cancer cell surface, which will attract and activate NK cells and other effector cells into the tumor." (PMID 34077462, 2021). "Although all of them seem to be over-expressed by different tumor cells, more knowledge has been obtained for MICA and MICB." (PMID 34394116, 2021). "NK cell-mediated ADCC against MICA/B bearing differentiated tumor cells in the presence of MICA/B antibody was compared to that mediated by the antibodies against EGFR and PDL1." (PMID 33440654, 2021). "We studied the relevance of the MICA alleles, both MICA-sequence and MICA-STR, on the clinicopathological characteristics of the tumor." (PMID 33868281, 2021). "We coupled the MICAB1-Fc silent mAb to potent DNA binder payloads, to promote the killing of MICA/MICB-expressing tumor cells." (PMID 35967081, 2021). "ADAM-dependent shedding of the major histocompatibility complex class I-related chain A (MICA) expressed by tumor cells prevents recognition by the NKG2D receptor expressed by natural killer (NK) cells thereby contributing to evading anti-tumor immunity." (PMID 33805340, 2021). "Various studies have shown that the shedding of MICA on the surface of tumor cells is increased by proteases, including metalloproteinases (MMPs) and a disintegrin and metalloproteases (ADAMs)." (PMID 34502191, 2021). "I-BET151 targets BRD4 in multiple myeloma cells and inhibits the expression of C-MYC and IRF4, thereby improving the transcription and translation levels of MICA, promoting the degranulation of NK cells and inducing anti-tumor immune response." (PMID 34540687, 2021). "As a consequence, increased MICA expression at the surface of HCC cell lines are detected, increasing NK cell-mediated tumor cell lysis in an NKG2D-MICA dependent manner." (PMID 34445750, 2021). "In our study, the MICA gene was highly expressed in the tumor tissues of COAD patients, which is consistent with some previous results." (PMID 33909599, 2021). "MICA/B expression is found on a broad range of solid and hematopoietic tumour cells as a result of cellular stress mechanisms to trigger activation signals in NKG2D-expressing NK and T cells." (PMID 34897554, 2021).
tumor (continued). "BLS-MICA elicited high titers of anti-MICA Ab in mice that in vitro recognized MICA naturally expressed on the cell surface of human tumor cells and on MICA-transduced mouse tumor cells." (PMID 34394116, 2021). "Hypoxia/HIF can upregulate the expression of metalloproteinase ADAM10, which is responsible for the shedding of the ligand MHC-I polypeptide-related sequence A (MICA) from the surface of tumour cells." (PMID 33923305, 2021). "For example, some tumor cells develop the capacity to discard MICA molecules off the cell surface using proteolysis, a process known as “MICA shedding”." (PMID 34943820, 2021). "Proteolytic shedding of MICA’s ectodomain is one of the major mechanisms used by tumor cells to escape from NK cell-mediated killing." (PMID 34925361, 2021). "The NK cell activating ligand MICA/B showed higher expression in the MDA-MB-231 tumor tissue than in RT-R-MDA-MB-231 or CD24−/low/CD44+ tumor tissue." (PMID 34502547, 2021). "The secretion of IL-8, IL-10 and TGF-β acts on NK cells and tumor cells and induces MICA/B shedding, the downregulation of MHC-Class I and the impairment of NK cell activity." (PMID 34445750, 2021). "Immunization of mice with BLS-MICA led to the generation of high titers of anti-MICA antibodies, which during in vitro experiments neutralized the MICA ligand expressed on the cell surface of human tumor cells." (PMID 34835294, 2021). "Tumor cells are known to upregulate major histocompatibility complex-class I chain related proteins A and B (MICA/B) expression under stress conditions or due to radiation exposure." (PMID 33440654, 2021). "Recent studies also support this notion by showing the upregulation of MICA/B on multiple tumor cell types via the PI3K/Akt pathway." (PMID 33918810, 2021). "In the same context, the circular lncRNA circ_0000997 was found to be a central regulator of hypoxia-induced resistance of pancreatic cancer (PACA) cells to NK-mediated killing, via promoting MICA shedding from tumor cell membranes." (PMID 34943820, 2021). "Natural killer group 2D (NKG2D) receptors activated on the surface of NK cells can bind to MICA to activate NK cells and kill tumor cells." (PMID 34540687, 2021). "Tumor-associated markers can also be detected by receptor–IgG chimeric proteins, such as NKG2D-IgG that binds MICA and MICB, ligands that are upregulated in various malignancies." (PMID 33467027, 2021). "Release of MICA from tumor cells can significantly suppress the NKG2D expression on NK cells in HCC patients." (PMID 33262461, 2021). "It has been previously shown that they enhance NK cell-mediated tumor cell targeting by upregulating the stress-inducing ligands MICA, MICB, and ULBP1-3 in tumor cells permitting a more efficient killing of tumor cells." (PMID 34957134, 2021). "This strategy was shown to prevent MICA/B shedding and to increase their expression on the tumor surfaces, ultimately inducing potent NK cell activity and inhibiting tumor growth." (PMID 32153582, 2020). "This monoclonal antibody (7C6) has been previously shown to be able to specifically target MICA/B a3 domain on tumor cells, resulting in the increase in cell surface MICA/B expression by inhibition of their shedding." (PMID 32645836, 2020). "In vivo evaluation of the therapeutic efficacy of such antibodies in syngeneic and immunocompetent mouse tumor models requires inoculation of mouse tumor cells ectopically expressing MICA." (PMID 32582150, 2020). "We also confirmed the immunological supposition that MICAgen mice are immunotolerant for MICA, which renders them a valuable tool for in vivo experiments with MICA-expressing tumor cells and/or MICA-targeting antibodies." (PMID 32582150, 2020). "In order to further validate that serum sMICA blocks killing of tumor cells by NK cells, we used human fibroblasts that stably express MICA as the target cells." (PMID 32010486, 2020).